CDCP1 (CUB domain containing protein 1)
Diseases named in the same sentence as CDCP1 in open-access papers (continued):
Sharing a sentence is not in itself a finding about the gene and the disease.
tumor (continued). "Regarding the mechanism of CDCP1 against anoikis, a few studies have proven that Ras activated CDCP1; subsequently, Tyr734 of CDCP1 bound to Fyn and was phosphorylated to activate protein kinase Cδ (PKCδ) and inhibit autophagy, helping tumor cells to escape apoptosis." (PMID 36230714, 2022). "Analysis of the expression levels of METTL3 and CDCP1 in patients with BCa revealed that METTL3 and CDCP1 were strongly upregulated in the tumor samples, and the METTL3-CDCP1 axis could increase the tumor proliferation, migration, and invasion." (PMID 35148766, 2022). "A large number of studies have shown that CDCP1 affects patient prognosis by affecting the tumor." (PMID 35410293, 2022). "The growth of 4T1 tumors was greatly suppressed in CDCP1 peptide-immunized mice, and the tumor size was smaller, the growth curve slower, the tumor weight lower, and the photon flux in lung metastasis lower compared to those in control PBS/Freund's adjuvant-immunized mice." (PMID 32308755, 2020). "Nevertheless, because PDAC has an extraordinarily dense fibrotic stroma that impedes tumor perfusion and delivery of anticancer agents 31 it is possible that CDCP1-targeted agents could fail in these patients." (PMID 32226543, 2020). "This revealed that CDCP1 mRNA expression level is associated with tumor size (p=0.011) but not with age, gender, tumor stage, vasculature invasion or lymph node positivity (data not shown)." (PMID 32226543, 2020). "However, the difference of the redox parameters between CDCP1– and CDCP1+ fractions was negligible in wtKras tumor cells (DKO3 and HKe3)." (PMID 31461438, 2019). "CD318, also known as CUB domain-containing protein 1 (CDCP1) or transmembrane and associated with Src kinases (TRASK), is present on epithelial cells, hematopoietic cells, MSCs, and tumor cells." (PMID 31828070, 2019). "These animal data provide further evidence to the hypothesis that CDCP1 expression is a direct consequence of RAS dependent MAPK signaling even in the complex milieu of a tumor." (PMID 29359686, 2018). "Treatment with a miR-1 inhibitor restored CDCP1 protein levels and enhanced tumor cell mobility." (PMID 28537886, 2017). "In N-positive TNBCs, for example, CDCP1 might promote transendothelial migration of TNBC cells or confer properties to tumor cells that have disseminated that improve their survival in circulating blood." (PMID 27626701, 2016). "Its potential as a target is supported by reports that five anti-CDCP1 antibodies, or antibody fragments, have demonstrated the ability, in in vivo models, to inhibit tumor growth or metastasis, with one of these antibodies successfully tested in a breast cancer tumor regression model." (PMID 26973855, 2016). "This allowed us to hypothesize that concomitant use of therapeutic antibodies against gene products of CD147 and CDCP1, combined with actin polymerization inhibitors (e.g., formin), may facilitate a more effective arrest of tumor invasion and metastasis." (PMID 27894102, 2016). "CDCP1 has emerged as an important tumor-regulating membrane bound protein." (PMID 26497208, 2015). "However, in model systems in which CDCP1 expression is dysregulated it provides clear tumor promoter activities." (PMID 26497208, 2015). "Furthermore, relative expression levels of ADAM9 and CDCP1 in tumor compared to normal part were measured among these samples." (PMID 26553452, 2015). "It has been suggested that CDCP1 acts as an oncogene, or, on the contrary, as a tumor suppressor." (PMID 25876044, 2015). "CDCP1 protein is released by the EVs and could play a role in the extravasation of tumour cells to organ specific metastasis." (PMID 25469109, 2014). "CDCP1 has been proposed to either positively or negatively regulate tumour metastasis." (PMID 25301083, 2014).
tumor (continued). "While there are numerous studies on the expression of CDCP1 in tumors or tumor derived cell lines, little is known about the CDCP1 - Src signaling complex and its regulation or how their interaction could promote cell transformation." (PMID 23300860, 2012). "To further confirm whether apoptosis induction occurs in a tumor-specific manner, we overexpressed Dro or CecA1 specifically in the FB of normal larvae and investigated apoptosis in larval tissues such as imaginal discs using anti-cDcp1 immunostaining." (PMID 40136638, 2025). "In addition, CDCP1 protein was also overexpressed in tumor samples in the CPTAC cohort." (PMID 36090897, 2022). "In addition, our flow cytometry results suggest that ex vivo evaluation of levels of cell surface CDCP1 in tumor biopsies or circulating malignant cells could also serve to stratify patients for CDCP1-targeted therapies." (PMID 36276654, 2022). "However, both tumor volume and weight were restored after overexpression of CDCP1." (PMID 33882457, 2021). "Similarly, the novel human antibody 4A06 (which recognises CDCP1) radiolabelled with zirconium-89 (89Zr-4A06) was able to detect CDCP1 expression, while the therapeutic constructs of the antibody (177Lu-4A06 and 225Ac-4A06) inhibited the growth of pancreatic subcutaneous xenograft tumours in mice." (PMID 33917882, 2021). "However, while such tumor-related metabolic adaptations characterize bulk tumor cells, it is unclear whether colon CDCP1+ CSCs exhibit a similar metabolic phenotype." (PMID 31461438, 2019). "Thus, CDCP1 displays a profound structural/functional shift concomitant with tumor progression." (PMID 26497208, 2015). "With respect to CDCP1 expression, the investigated xenografts could be subdivided into three groups: five models with 0.4% to 2.8% of positive cells; a group of four with expression levels between 6.3% and 9.9%; and the six remaining tumours comprised 16.7% - 32.7% CDCP1 positive cells." (PMID 22433494, 2012). "These novel observations may indicate that KAI1 exerts profound metastasis-suppressor activity in the tumor malignancy process via inhibition of CDCP1-mediated Src activation, followed by VHL-induced HIF-1α degradation and, ultimately, decreased VEGF expression." (PMID 22390300, 2012). "Notably, expression of the tumour marker Ceacam6 and Cdcp1 were upregulated as was prostaglandin synthase 2 (Ptgs2) that might lead to a modified arachidonic acid metabolism pertinent to the respiratory epithelium." (PMID 21152443, 2010). "Histological and multiplex immunofluorescence analyses confirmed that NSUN2 deletion reduced tumor-induced PNI and downregulated CDCP1 and STC1, while lactate supplementation increased pan-lactylation, NSUN2, CDCP1, and STC1 expression." (PMID 41356184, 2026). "We previously developed two antibody clones: 4A06, which targets both full-length and cleaved forms of CDCP1, and CL03, which selectively recognizes the cleaved form for enhanced tumor specificity." (PMID 40661577, 2025). "Upregulated CDCP1 activated Src/PKCδ signaling, facilitating EMT and CAF activation within the tumor microenvironment." (PMID 41301830, 2025). "Vascular invasion within the tumor and high expression of CUB domain-containing protein (CDCP1) and low levels of insulin-like growth factor binding protein (IGFBP5 and IGFBP7) in the bloodstream have been reported as risk factors for lymph node recurrence." (PMID 38472943, 2024). "In conclusion, this study demonstrated overexpression of ADAM9, CDCP1, and t-PA in OSCC, which were positively correlated with tumor cell differentiation of OSCC." (PMID 39441449, 2024). "The results by Spearman correlation test showed that overexpression of ADAM9, CDCP1, or t-PA in OSCC was positively correlated with distinct degrees of tumor cell differentiation, as defined by different histopathological diagnoses." (PMID 39441449, 2024).
tumor (continued). "More recently, cub-domain containing protein-1 (CDCP1)- targeting 89Zr-radiolabeled antibodies 4A06 and 10D7 demonstrated effective detection of PDAC tumours in vivo using PET imaging." (PMID 35204653, 2022). "Then, bioinformatics analysis and experimental verification demonstrated that CDCP1's function is mainly related to EMT and immune infiltration, which are highly consistent with the characteristics of MES-GBM and the tumor microenvironment." (PMID 35410293, 2022). "Although IHC analysis confirmed nearly 100% downregulation of CDCP1 expression in CRC13-shCDCP1 compared to CRC13-shSrc tumors, tumor avidity varied by 40%." (PMID 34621145, 2021). "Furthermore, CUB domain-containing protein 1 (CDCP1) derived from radiation-induced sEVs was identified as a novel tumor-associated antigen and developed as a peptide vaccine that may generate antitumor immune responses." (PMID 32308755, 2020). "Targeting CDCP1 impairs PDAC cell functions and PDAC tumor growth independently of CDCP1 cleavage status." (PMID 32226543, 2020). "TNBC, a highly metastatic tumor, expresses the protein CUB-domain containing protein 1 (CDCP1), which activates acyl-CoA synthesis to increase FAO." (PMID 33291682, 2020). "The absence of an association of CDCP1 expression and copy number gains with clinicopathological features or the expression of a basal-like BC marker, such as cytokeratin 5/6, suggests that CDCP1 is already present in early-stage TNBCs, independent of the molecular phenotype of tumor cells." (PMID 27626701, 2016). "In skin epidermal cells and epithelial tumor cells, PKC-δ is known to bind to CDCP1 after stimulation." (PMID 25275584, 2014). "Outcomes beyond CDCP1 participation in the phosphorylation by SFK and the regulation of PKC-δ is suggested by metastasis and survival of tumor cells." (PMID 25275584, 2014). "We followed tumor growth in vivo and immunohistochemistry was performed for detection of HIF-1, CDCP1, and VHL protein level." (PMID 22390300, 2012). "We observed no significant change in combined tumor volume, but lung metastases were significantly reduced in mice implanted with CDCP1 knockout cells compared to mice with gGFP cells." (PMID 40908298, 2025). "Interestingly, most CIDGS-related genes, such as XRCC6, ST13, PES1, EFHD2, APOL2, ACTR2, and CDCP1, were markedly upregulated in HNSCC tumor samples, whereas several other genes, such as MARCO, MRC1, and CD83, were upregulated in healthy samples." (PMID 38666027, 2024). "CDCP1 is a transmembrane glycoprotein that is not cleaved by serine proteases under normal physiological conditions but can be cleaved in response to tumor or tissue damage." (PMID 39441449, 2024). "The expression of CDCP1 was not related to tumor differentiation, T stage, AJCC stage, and HER2 status." (PMID 36090897, 2022). "The results exhibited that CDCP1 was not varied in tumor tissues with different TNM stages, but upregulated in HER-positive and triple-negative subtypes." (PMID 36090897, 2022). "A CDCP1-targeting antibody is highly effective at delivering imaging radionuclides and cytotoxins to PDAC cells allowing specific detection of tumors by PET/CT imaging and superior anti-tumor effects compared to gemcitabine in in vivo models." (PMID 32226543, 2020). "Although CDCP1 is commonly cleaved in patient-derived PDAC cells, our data suggest that its proteolysis is not a significant contributor to the PDAC cell movement, resistance to chemotherapy and primary tumor growth that we observed in our assays." (PMID 32226543, 2020). "As compared to the CDCP1– fraction in muKras tumor cells (DKs5 and HK2-10), CDCP1+ CSCs exhibited relatively lower levels of intracellular ROS, accompanied with remarkably higher levels of the [NADPH/NADP+] and [glutathione/glutathione disulfide] ([GSH/GSSG]) ratios." (PMID 31461438, 2019).
tumor (continued). "We found that knockdown of CDCP1 or ITGB5 slows the growth of cells addicted to RAS signaling, supporting the idea that oncogenic RAS promotes the expression of these proteins to enable tumor cell growth." (PMID 29359686, 2018). "CD133, CD44, CD24, CDCP1, CXCR4, and CD26 have been identified as colon CSC surface antigens, but it is not well defined which are the best markers to identify a tumor stem cell due to the variability found among individuals with the same tumor type." (PMID 25685060, 2015). "Moreover, whereas CDCP1 and HIF-1α expression were reduced in KAI1-expressing tumor tissue, VHL expression was clearly augmented." (PMID 22390300, 2012). "Next, we performed immunohistochemistry to detect HIF-1α, CDCP1 and VHL protein in tumor tissue." (PMID 22390300, 2012). "Moreover, t-PA expression in OSCC was significantly enhanced in advanced pTNM stages and large tumor size, but not with the presence of cervical lymph node metastasis, whereas CDCP1 expression in OSCC was unaffected by any clinical variables." (PMID 39441449, 2024). "In contrast, cells were highly proliferative regardless of CDCP1 status in wtKras tumor cells." (PMID 31461438, 2019). "Dox treatment alone failed to eradicate CDCP1+ cells and therefore had no impact on tumor growth." (PMID 31461438, 2019). "Regarding tumor nests, 57% (37/65) of cases were CDCP1-positive, 45% (29/65) was PDGFRβ-positive, 32% (21/65) was positive for CDCP1 and PDGFRβ (double-positive), and 31% (20/65) was negative for CDCP1 and PDGFRβ (double-negative)." (PMID 29792166, 2018). "However, supporting that several growth factor receptors can regulate the expression of CDCP1, not all CDCP1-positive specimens expressed PDGFRβ in the tumor cells." (PMID 29792166, 2018). "Importantly, KAI1 inhibited the expression of CDCP1 and HIF-1α in an in vivo tumor xenograft model." (PMID 22390300, 2012). "To see whether this protein has tumor promoting effects in the NIH3T3 cell system, we generated a specific retrovirus and employed it either alone, together with Src or Src plus CDCP1 in focus formation assays (data not shown)." (PMID 23300860, 2012). "However, although METTL3-m6A-CDCP1 axis can promote the proliferation and migration of SV-HUC-1 uroepithelial cells in vitro, injection of METTL3 or CDCP1-overexpressing SV-HUC-1 cells into immunodeficient mice did not induce tumor formation in vivo (data not shown)." (PMID 30796352, 2019).
infection (6 papers, 2012 to 2025). The state of being infected such as from the introduction of a foreign agent such as serum, vaccine, antigenic substance or organism. "On the other hand, a CDCP1 encoding virus where all of the intracellular tyrosines except for the residue at position 734 were mutated to phenylalanine, reproducibly yielded slightly more foci than infection with the Src virus alone or coexpression of Src and a Y/F mutant." (PMID 23300860, 2012). "For CDCP1, an obvious increase in RNA expression was observed upon infection, a result further confirmed through quantitative real-time PCR where CDCP1 exhibited a 100% upregulation." (PMID 39467689, 2024). "As above, the combined infection with Src and CDCP1 wild type retroviruses enhanced focus formation strongly." (PMID 23300860, 2012). "Based on these results, the CUB domain-containing protein 1 (CDCP1) screened at the 12th infection week could be investigated further." (PMID 36986363, 2023). "In this assay, upon infection of the cells with retrovirus encoding wild type CDCP1 we did not observe the formation of foci that appear when cells are transformed and grow on top of each other because of loss of contact inhibition." (PMID 23300860, 2012). "The combination treatment with both TMAO and CFT073 had significant additive effects on the release of PD-L1 and STAMBP and synergistic effects on the release of CDCP1, uPA, AXIN1, MMP-10, and CD40 compared to CFT073 infection alone." (PMID 37111409, 2023). "Namely, CD5, CD8A, CD6 and CD244, C-C and C-X-C motif chemokines (CXCL5 CXCL6, MCP-4, and CCL20), as well as CD40, PDL-1, CUB domain-containing protein 1 (CDCP1) and interleukin-12B (IL-12B) were elevated in the late infection group compared to the unexposed group." (PMID 41510260, 2025).
adenocarcinoma (4 papers, 2021 to 2025). A common cancer characterized by the presence of malignant glandular cells. "Histological analysis of representative untreated subcutaneous HCT116 tumors revealed that xenografts display adenocarcinoma histological features and CDCP1 expression which is located predominantly on the surface of malignant cells." (PMID 34621145, 2021).
cardiovascular disease (2 papers, 2023 to 2025). "Furthermore, many of the age-associated proteins such as CST5, CCL23, SLAMF1, MMP-1, MCP-1, and CDCP1 have been linked to chronic diseases such as cardiovascular disease and neurocognitive decline in the general population." (PMID 37672793, 2023).
heart disease (2 papers, 2025). "The Kaplan-Meier curve revealed a significant difference in ischaemic heart disease risk between groups with low versus high CDCP1 levels (Log-rank p = 0.032)." (PMID 40684041, 2025). "Importantly, an externally validated inflammatory marker CDCP1 was associated with higher risk of incident ischaemic heart disease." (PMID 40684041, 2025). "Notably, CDCP1 consistently associates with future ischaemic heart disease, suggesting a potential biological pathway connecting social disadvantage, inflammation, and cardiovascular health." (PMID 40684041, 2025). "Among these, TNFSF14, HGF, CDCP1, and CCL11 were also associated with increased cardiovascular risk, and CDCP1 was further linked to future heart disease events." (PMID 40684041, 2025). "Proteins such as CDCP1, CXCL17, FGF21, GDF15, and IGFBP4 commonly mediated effects in both the Air and Noise Pollution and Social Deprivation groups, while GDF15 was notably linked to heart disease across these patterns." (PMID 41290610, 2025).
inflammation (1 paper, 2023). Aberrant reaction of the microcirculation characterized by movement of fluid and leukocytes from the blood into extravascular tissues. "This, together with the fact that CDCP1 showed no negative correlation to the degree of fibrosis but rather to NAFLD Activity Score (NAS) as a measurement of disease activity (data not shown), suggested that CDCP1 levels instead associated with active liver inflammation." (PMID 37342340, 2023).
kidney disease (1 paper, 2024). "We also found, using the Olink proteomic platform, that TNF-α and TMAO enhanced the secretion of additional inflammatory-and growth mediators associated with kidney disease; VEGFA, GDNF, CDCP1, OPG, uPA, AXIN1, MMP-1, MMP-10, PD-L1, HGF, Flt3L, 4E-BP1, CD40, CASP-8, ADA, TNFRSF9, TWEAK44–61." (PMID 38643262, 2024).
CDCP1 also shares sentences with these, for which no sentence is quoted: autoimmune disease (4 papers); pancreatic adenocarcinoma (4); breast tumor (2); cervical squamous cell carcinoma (2); colon adenocarcinoma (2); kidney cancer (2); lung squamous cell carcinoma (2); ovarian serous cystadenocarcinoma (2); renal cell carcinoma (2); urothelial carcinoma (2); adrenocortical carcinoma (1); astrocytoma (1); attention deficit-hyperactivity disorder (1); bladder tumors (1); bladder urothelial carcinoma (1); brain tumor (1); Burkitt lymphoma (1); cataract (1); cholangiocarcinoma (1); clear cell renal cell carcinoma (1); colorectal adenocarcinoma (1); cystitis (1); endocervical adenocarcinoma (1); experimental autoimmune encephalomyelitis (1); fibrosis (1); head and neck squamous cell carcinoma (1); hematological malignancies (1); Hyperinsulinemia (1); Hypoglycemia (1); inflammatory skin disease (1).
A further 19 diseases each share a sentence with CDCP1 in 1 paper.